MGMT (O-6-methylguanine-DNA methyltransferase)
Diseases named in the same sentence as MGMT in open-access papers (continued):
Sharing a sentence is not in itself a finding about the gene and the disease.
glioma (continued). "The results indicated IDH1 mutate, 1P19 codeletion, ATRX and MGMT as robust favorable clinical prognostic indicators, while PCK2 along with age (PCK2, TCGA: P<0.0001, CGGA: P<0.0001) serve as indicators for poor survival time in glioma patients." (PMID 39744481, 2025). "This aspect may relate to angiogenesis in GBM, with MGMT unmethylated tumors possibly exhibiting a higher level of angiogenesis as compared to MGMT methylated tumors, as reflected in angiogenesis pathways and glioma subtypes overall." (PMID 40428285, 2025). "As an important DDR protein, MGMT is widely expressed in normal human tissues but is generally expressed at high levels in all types of human tumours, including melanoma, lung cancer, glioma, leukaemia, lymphoma and colon cancer." (PMID 39873425, 2025). "However, in contrast to GBM, which typically loses one copy of chromosome 10 where the gene encoding MGMT is located, lower-grade IDH-mutant gliomas usually retain both copies." (PMID 40428422, 2025). "Importantly we observed unique cytokine profiles and suppression of MGMT expression in glioma cell lines by imipridones ONC201 and ONC206 as potential synergy mechanisms with TMZ." (PMID 40145650, 2025). "Furthermore, AR expression was more frequent in MGMT-unmethylated gliomas compared with MGMT-methylated tumors (p = 0.02)." (PMID 41153666, 2025). "While maximal safe resection remains the goal in glioma surgery, intraoperative MGMT estimation may refine judgment in eloquent areas." (PMID 41247617, 2025). "A striking progression has been the joining of atomic markers such as IDH1/2 transformations, MGMT promoter methylation, EGFR amplification/mutations, and 1p/19q codeletion into the symptomatic criteria for gliomas, as laid out by the WHO CNS tumor classifications." (PMID 41311621, 2025). "MGMT promoter methylation is an independent prognostic predictor for glioma patients." (PMID 40090864, 2025). "Compared with established molecular markers used in glioma molecular subtyping, such as IDH mutation, 1p/19q deletion, and MGMT methylation status, the open chromatin feature-based methods could capture the characteristics of glioma in a dynamic way." (PMID 41473442, 2025). "Results of multivariate logistic regression with bootstrapping (1,000 samples) for prediction of O6-methylguanine-DNA methyltransferase (MGMT) methylation in high grade gliomas showing separate models for DeepBraTumIA ratio, DeepBraTum peritumoral edema and Raidionics ratio." (PMID 41476598, 2025). "Indeed, it was found that inactivation of MGMT by methylation of its promoter leads to improved clinical response of gliomas to alkylating agents and specifically to temozolomide." (PMID 39796751, 2025). "MGMT promoter methylation is of importance in glioma regarding prognosis and management." (PMID 41247617, 2025). "In terms of the MGMT promoter methylation status, 27 patients had MGMT-methylated gliomas, 15 had MGMT-unmethylated gliomas, and the MGMT methylation status of one was unknown." (PMID 40746950, 2025). "In contrast, those with MGMT-unmethylated gliomas had the shortest OS, just 13 months." (PMID 40746950, 2025). "Notably, patients with MGMT-methylated grade 4 gliomas treated with the BAC regimen had the longest median OS, 33 months." (PMID 40746950, 2025). "Besides, two RCTs both certified the prognostic advantage in glioma patients with MGMT hypermethylation after the administration of both ART and temozolomide." (PMID 40567901, 2025). "With respect to the MGMT promoter methylation status, 12 patients had MGMT-methylated gliomas, 6 had MGMT-unmethylated gliomas, and the MGMT methylation status of 5 was unknown." (PMID 40746950, 2025).
glioma (continued). "Moreover, AR expression was more frequent in MGMT-unmethylated gliomas compared with MGMT-methylated tumors (p = 0.02)." (PMID 41153666, 2025). "However, glioma cells capable of reversing guanine methylation via the repair enzyme O6-methylguanine DNA methyltransferase (MGMT) are resistant to TMZ." (PMID 40336841, 2025). "However, GBM evades TMZ toxicity through DNA repair via O6-methylguanine-DNA methyltransferase (MGMT), cellular plasticity and glioma stem cells (GSCs)." (PMID 40313865, 2025). "Consequently, MGMT promoter methylation status has become integral to clinical decision-making in glioma management, informing treatment protocols and potentially improving survival rates." (PMID 39941181, 2025). "The prognostic significance of USP7 and MGMT in gliomas was assessed using the PrognoScan database." (PMID 40835840, 2025). "With respect to the MGMT promoter methylation status, 8 patients had MGMT-methylated gliomas, 15 had MGMT-unmethylated gliomas, and the MGMT methylation status of 6 was unknown." (PMID 40746950, 2025). "In addition, histogram DCE-MRI also showed good diagnostic performance in predicting O6-methylguanine-DNA methyltransferase (MGMT), telomere reverse transcriptase (TERT), and evaluating the prognosis of glioma." (PMID 40134593, 2025). "Amongst all IDH1/2-mutant gliomas, 64.1% were MGMT methylated." (PMID 39164213, 2025). "These new pathways of MGMT inhibition greatly sensitized gliomas to alkylating agents." (PMID 39997039, 2025). "The expression by transfection enhanced responsivity of TMZ in MGMT-expressing T98G glioma cells." (PMID 40141375, 2025). "However, more than 50% of patients eventually develop resistance, often due to MGMT overexpression, enhanced DNA repair, the presence of glioma stem-like cells, and activation of the prosurvival pathway." (PMID 41429922, 2025). "Gliomas with IDH mutations, 1p19q codeletions, and MGMT promoter methylation demonstrated significantly lower RSF scores compared to their respective control groups, indicating that RSF scores may reflect underlying molecular alterations." (PMID 40264576, 2025). "In summary, the differences in MGMT promoter methylation between genders could potentially explain some variance in the clinical outcomes seen in glioma patients." (PMID 39834719, 2025). "The DNA repair protein O6-methylguanine-DNA methyltransferase (MGMT) may cause resistance of tumor cells to alkylating agents and is a predictive biomarker in high-grade gliomas treated with temozolomide." (PMID 40444102, 2025). "Second, by stratifying gliomas according to IDH status—a critical molecular determinant of tumor biology—we reveal that MGMT promoter methylation significantly correlates with elevated rADCmin exclusively in IDH-wildtype gliomas (AUC = 0.78, sensitivity = 80.0% at cutoff 1.10)." (PMID 40958862, 2025). "Moreover, MGMT-methylated gliomas demonstrated a higher CBF measured by the ASL, as compared to LGGs." (PMID 40870498, 2025). "This method was able to reduce data dimensionality and represent it on a 2D perceptual map, revealing associations between various established glioma prognostic factors, including histological classification, IDH status, MGMT promoter methylation, and transcriptome subtypes." (PMID 41342138, 2025). "Additionally, the methylation status of MGMT mainly affects the sensitivity of patients with glioma to chemotherapeutic drugs." (PMID 40352771, 2025). "Although contemporary glioma clinical practice relies on multiple established biomarkers—including MGMT promoter methylation status, IDH, genetic alterations beyond 1p/19q and adjuvant therapies—these markers primarily focus on single therapeutic contexts or specific pathological subtypes." (PMID 41049291, 2025). "In high-grade gliomas such as GBM, MGMT methylation is less frequent compared to low-grade gliomas." (PMID 39768232, 2024).
glioma (continued). "It is anticipated that further investigation into TRIB3 and AURKA could lead to the development of novel therapeutic targets for glioma, such as MGMT and EGFR." (PMID 39118481, 2024). "The contribution of this study is 2-fold: one is to confirm the possibility of predicting the methylation status of MGMT promoter in gliomas by WSI; second, an end-to-end model was established to simplify the cost of MGMT promoter status detection in glioma patients." (PMID 38385046, 2024). "MGMT-methylated was set as the base category, due to its characteristic of providing a better prognosis for patients, with predictor features being used to estimate the likelihood of a glioma being MGMT-unmethylated." (PMID 38167551, 2024). "In other words, radiomic models considering heterogeneous glioma grades perform better because they may be influenced by the different levels of MGMT promoter methylation between lower- and higher-grade gliomas." (PMID 38308012, 2024). "In addition, EGFR + TNF inhibition is more effective than temozolomide treatment in glioma cells where methylguanine methyltransferase (MGMT) is unmethylated, whereas it is comparable in MGMT methylated cells." (PMID 38561856, 2024). "Furthermore, multimodal MRI parameters were selected to establish models for predicting MGMT methylation in the IDH-wildtype gliomas." (PMID 39594235, 2024). "We therefore interrogated whether rapamycin altered the expression of MGMT in MGMT promotor unmethylated glioma cells thereby antagonizing temozolomide." (PMID 38182566, 2024). "Therefore, patients with a methylated MGMT gene promoter region in glioma cells respond better to TMZ." (PMID 39246656, 2024). "MGMT activity was most pronounced in liver, ovarian, and colon tumors, yet it remained notably low in gliomas, which may have contributed to the sensitivity of glioma cells to temozolomide therapy." (PMID 38255825, 2024). "Moreover, knockdown of SP1 strongly reduces MGMT protein expression, further suggesting SP1’s role as a main regulating factor for MGMT expression in glioma cells." (PMID 38521933, 2024). "Among its most recent contributions, one study elucidated that the application of epigenetic editing technologies to modulate MGMT methylation status, or to regulate its methylation patterns in a rhythmic manner, can significantly impact the chemosensitivity of gliomas to temozolomide." (PMID 39286478, 2024). "In conclusion, we have generated insight into the impact of epigenetic modification of the MGMT promoter region for temozolomide sensitivity of glioma cells and may serve as a proof of concept for future studies." (PMID 38357209, 2024). "However, as far as we know, research regarding MGMT promoter methylation in glioma using pathological images remains relatively limited." (PMID 38385046, 2024). "We divided gliomas into high-risk or low-risk groups based on median signature, and found significant enrichment of older age, WHO grade 4, IDH-wildtype, 1p/19p intact, MGMT promoter unmethylation and mesenchymal subtype in the high-risk group." (PMID 39121828, 2024). "Therefore, the non-invasive assessment of MGMT methylation in gliomas is essential to guide the selection of individualised chemotherapeutic agents." (PMID 39594235, 2024). "In MGMT promotor unmethylated glioma cells mTOR inhibition led to an induction of MGMT which may explain the protective effect despite the lack of effect on ROS levels in these cells." (PMID 38182566, 2024). "Therefore, we present the second advantage of our predictive model, which can reflect the mutational status of gliomas, wherein high-risk patients exhibit a lower frequency of IDH1 mutation, 1p/19q co-deletion and MGMT methylation." (PMID 39574472, 2024). "Consequently, we observed MGMT downregulation and enhanced glioma chemosensitivity in survival assays in vitro, with minimal off-target effects." (PMID 38224404, 2024).
glioma (continued). "Moreover, the PANRG score was also correlated to advanced age, worse OS status, higher glioma grade and MGMT promoter unmethylated." (PMID 38577605, 2024). "Conversely, gliomas with unmethylated MGMT typically display a ring-pattern enhancement." (PMID 39768232, 2024). "A more recent review from 2022 showed that gliomas with methylated MGMT promoter are typically found in the temporal lobe of the left hemisphere and display ring contrast-enhancement, more central necrosis, higher minimum apparent diffusion coefficient, and higher relative cerebral blood flow." (PMID 39531176, 2024). "Hypermethylation of CpG islands in the promoter region suppresses MGMT activity in glioma cells." (PMID 38893240, 2024). "Notably, in an orthotopic glioma model with O6-methylguanine-DNA methyltransferase (MGMT) methylation, the combination of AZD9574 with TMZ significantly extended survival compared to TMZ alone." (PMID 39399414, 2024). "The APT values of gliomas with unmethylated and methylated MGMT promoter were almost identical." (PMID 39272871, 2024). "Furthermore, another study assessed the effectiveness of nivolumab when combined with RT and TMZ, the standard of treatment, for patients with newly diagnosed MGMT methylated or indeterminate glioma." (PMID 39452154, 2024). "Furthermore, addition of MR diffusion to conventional MRI features significantly improved the diagnostic value in preoperative prediction of IDH1, MGMT, and ATRX in patients with glioma." (PMID 38486342, 2024). "MGMT promoter methylation status appears to be variably correlated with MRI radiomic features; radiomic models are not sufficiently robust to be integrated into clinical practice to accurately predict MGMT promoter methylation status in patients with glioma before surgery." (PMID 38308012, 2024). "Subject characteristics relative to glioma grade, IDH mutation, and MGMT methylation." (PMID 39100020, 2024). "we did not investigate whether CMTM5/WWP2/LATS2 signaling affects DNA repair enzyme O6Meg DNA methyltransferase (MGMT) status in glioma." (PMID 39166861, 2024). "These MRI findings may validate the theory that gliomas with MGMT-unmethylated possess intact DNA repair mechanisms, enabling continuous tumor proliferation and reduction in the effectiveness of chemotherapy agents." (PMID 38167551, 2024). "MGMT methylation is another important molecular marker in glioma management." (PMID 38167551, 2024). "In gliomas, the MGMT promoter methylation status is of significant interest." (PMID 38167551, 2024). "While there have been multiple attempts to overcome MGMT-mediated TMZ resistance in glioma cells, by means such as siRNA, enzymatic inhibition or knock-out, the specific induction of individual CpG methylation has so far not been recreated in a laboratory environment." (PMID 38357209, 2024). "In addition to current well-known indicators of glioma prognosis, such as IDH mutation, 1p/19q co-deletion and MGMT promoter methylation, the risk score also represents a significant independent predictor for overall survival." (PMID 38515213, 2024). "More precise subcategorization of treatment criteria has been introduced to the new edition of the WHO recommendations on glioma for patients with various prognoses and medication sensitivity, including isocitrate dehydrogenase IDH mutations, 1p/19q co-deletions, and MGMT promoter methylation." (PMID 38396140, 2024). "It was revealed that GSN was enriched in IDH‐wild‐type and MGMT unmethylated glioma." (PMID 38803199, 2024). "Approximately 40% of gliomas exhibit MGMT methylation, leading to decreased MGMT expression i.e., decreased DNA repair and therefore to an enhanced sensitivity to TMZ, which significantly prolongs survival compared to patients without the methylation of this site." (PMID 39767640, 2024).
glioma (continued). "O6‐methylguanine‐DNA‐methyltransferase (MGMT) promoter methylation serves as a significant molecular marker for assessing the therapeutic efficacy of alkylating agents like temozolomide, which is a first‐line chemotherapy drug for glioma." (PMID 39252824, 2024). "MGMT methylation status is another important molecular marker in glioma diagnosis." (PMID 38167551, 2024). "Moreover, we found that MGMT promoter methylation was more prevalent in female GBMs in the Chinese Glioma Genomic Atlas as well." (PMID 38491408, 2024). "However, multiple clinical trials using O6‐BG, which is a selective inhibitor of MGMT, to treat glioma revealed increased toxicity and more side effects." (PMID 39041891, 2024). "Myriapod® NGS OncoDNA (Gosselies, Belgium) offers a CE-IVD kit - OncoDEEP for sequencing of 638 genes in FFPE tissues including all marker genes for glioma but missing important CNVs (1p/19q-codeletion and chr +7/-10) and p-MGMT methylation (OncoDEEP - Comprehensive biomarker test, 2023)." (PMID 37908227, 2023). "Methylated DNA can have important implications and its analyses as biomarkers provides an additional tool for researchers and clinicians; for example, in gliomas, the most discussed epigenetic alteration is promoter hypermethylation of the gene for O6-methylguanine-DNA methyltransferase (MGMT)." (PMID 37090492, 2023). "And the MGMT methylation is one of the independent predictors of good prognosis of glioma patients." (PMID 36856519, 2023). "MGMT has been reported to be the core mechanism of TMZ resistance in gliomas." (PMID 36683086, 2023). "Knocking down PKN1 suppressed MGMT expression in glioma cells." (PMID 37480215, 2023). "However, in many other studies related to gliomas, MGMT status has also been considered a key indicator of patient prognosis." (PMID 37147573, 2023). "We found relevant data from 693 patients with glioma in the CGGA database and classified them according to age, gender, histology, tumor type, isocitrate dehydrogenase (IDH) mutation level, 1p19q level, and O-6-methylguanine DNA methyltransferase (MGMT) level." (PMID 37887529, 2023). "Our model was built with disulfidptosis‐related risk scores which showed both accurate prediction of the prognosis of glioma patients and excellent distinction for several glioma molecular subtypes including grade, IDH mutation, MGMT promoter methylation, and 1p19q codeletion status." (PMID 37864127, 2023). "Overall, these data indicated that RAD51AP1 facilitated DSB repair in MGMT-methylated glioma cells and could be a therapeutic target in this type of glioma." (PMID 37283490, 2023). "The different VAF/cellularity cutoffs for tumor types could be related to differences in intratumoral heterogeneity of MGMT promoter methylation in IDH-mutant versus IDH-wildtype gliomas." (PMID 37919784, 2023). "In addition, the relationship of risk score and several well-known biomarkers of glioma (IDH mutant, 1p19q co-deleted, and methylation of MGMT promoter) was analyzed to verify the clinical applicability of the signature." (PMID 37542290, 2023). "The Kaplan-Meier curves revealed that high ARPC5 expression predicts a poor prognosis for patients with grade II and III gliomas, and the same result was obtained for different molecular subtypes, such as gender, age, IDH mutation status, 1p/19q co-deletion status, and MGMT methylated status." (PMID 37789267, 2023). "Univariate Cox regression analysis showed that age, IDH (encoding isocitrate dehydrogenase) mutation status, 1p19q codeletion status, O6-methylguanine (O6-MeG)-DNA methyltransferase (MGMT) status, and RRPRS risk scores correlated significantly with the PFS of patients with glioma." (PMID 37700319, 2023). "The expression of MGMT may be regarded as the most significant molecular predictor of TMZ resistance and prognosis in gliomas, provided that the cytotoxic effects of the alkylating agent can be mitigated in cells with a high level of endogenous MGMT activity." (PMID 37630276, 2023).